RN7SL75P (RNA, 7SL, cytoplasmic 75, pseudogene)
Gene: Miscellaneous RNA gene on chromosome 9 (100,102,559 to 100,102,839, forward strand). Ensembl gene ENSG00000239908.
Homologues: Orthologues: chimpanzee Metazoa_SRP (98% identical), macaque Metazoa_SRP (96% identical). Paralogues in human: RN7SL2 (83% identical), RN7SL1 (83% identical), RN7SL3 (81% identical), RN7SL239P (80% identical), RN7SL296P (80% identical), RN7SL431P (80% identical), RN7SL516P (80% identical), RN7SL357P (80% identical), RN7SL660P (80% identical), RN7SL147P (79% identical), RN7SL326P (79% identical), RN7SL479P (79% identical), and 700 more.